IL6 (interleukin 6)
Diseases named in the same sentence as IL6 in open-access papers (continued):
Sharing a sentence is not in itself a finding about the gene and the disease.
lung carcinoma (785 papers, 1995 to 2026). "For example, the MEMA studies identified both TGF-β and IL-6 as enhancers of the growth and survival of lung cancer and HMEC cells, and both have long been associated with SASP." (PMID 41497628, 2025). "Recently, N-linked glycosylation of IL-6 at N73 was confirmed in IL-6 secreted from different lung cancer cells." (PMID 40663802, 2025). "The IL-6 protein concentration was higher in patients with lung cancer carrying the IL-6 rs1800796G allele compared with the C/C genotype." (PMID 40156608, 2025). "Another research on uranium miners unveiled an association between a specific IL-6 promoter polymorphism (rs1800797) and lung cancer." (PMID 40823246, 2025). "IL-6 polymorphisms are correlated with lung cancer risk, and the IL-6 rs1800796G > C polymorphism increases cancer susceptibility in Asian populations." (PMID 40156608, 2025). "Studies reveal elevated levels of IL-6 as a prognostic indicator associated with poor outcomes in multiple tumor types, including lung cancer." (PMID 41376623, 2025). "Overproduction of granulocyte colony-stimulating factor (G-CSF), granulocyte macrophage colony-stimulating factor (GM-CSF), and interleukin-6 in lung cancer has been linked to leukocytosis." (PMID 40114445, 2025). "Research evidence highlights IL-6 and IL-17 as diagnostic markers in lung cancer; of which IL-6, more than IL-17, was found to be significantly higher in the serum of patients with adenocarcinoma." (PMID 41376623, 2025). "This suggests it regulates the lung microenvironment via the “gut-lung axis”, e.g., by reducing pro-inflammatory cytokines (TNF-α, IL-6) and lowering lung cancer risk." (PMID 41003841, 2025). "Tumor-related inflammation is indicated by elevated levels of inflammatory markers (e.g., C-reactive protein, CRP; interleukin 6, IL-6) and has been linked to poor outcomes in a number of malignancies, including lung cancer." (PMID 39816276, 2024). "Among the list, the overexpression of IL-6 has been associated with the onset of signaling cascades in lung cancer, breast cancer, prostate cancer, and other human cancers." (PMID 38279220, 2024). "They discovered a notable association between lung cancer and the highest quartile of serum IL-6 levels (OR = 3.29, 95% CI: 1.88–5.77)." (PMID 38339264, 2024). "Those associated with lung cancer include interleukin-4 (IL-4), IL-6, monocyte chemotactic protein-1 (MCP-1), and tumor necrosis factor-alpha (TNF-α)." (PMID 39042180, 2024). "IL-6 levels were specifically elevated in WA lung cancer patients and associated with lung adenocarcinoma." (PMID 38276239, 2024). "Based on studies reporting a correlation between Stk11 loss and Il-6 upregulation in mouse models of Kras-driven lung cancers in vivo, we compared IL-6 expression between STK11 WT (aka “Parent”) and matched STK11-KO human LUAD cells using qRT-PCR." (PMID 37968341, 2024). "In a case–control study conducted at the National Cancer Institute in Maryland, Sharon R. Pine and colleagues analyzed the association between IL-6 and lung cancer in six pairs of patients and controls." (PMID 38339264, 2024). "Some recent studies have also shown an association between high baseline IL-6 levels and reduced benefits from immunotherapy in hepatocellular carcinoma, melanoma, renal cell carcinoma, lung cancer and cutaneous squamous cell carcinoma patients." (PMID 38776028, 2024). "Conversely, WA lung cancer patients showed heightened IL-6 levels, particularly linked to lung adenocarcinoma." (PMID 38276239, 2024). "A meta-analysis study has confirmed that IL-6-174G > C is an independent risk factor for lung cancer prevalence in Caucasian (OR 1.04, p < 0.001) and Asian populations (OR 1.05, P = 0.003)." (PMID 38103126, 2024). "In cisplatin therapy, increased IL‐6 secretion leads to tumor cell migration and proliferation, promotes lung cancer metastasis, and is associated with poor prognosis." (PMID 38125769, 2023).
lung carcinoma (continued). "In a study conducted in Australia and Sweden, increased levels of IL-6 had an association with the lung cancer risk among former smokers (OR [95% CI]: 2.70 [1.55–4.70]) and current smokers (OR [95% CI]: 1.99 [1.15–3.44])." (PMID 38067398, 2023). "Serum IL-6 and IL-8 were previously reported to increase the risk of lung cancer, and were significantly associated with tumour recurrence in Stage I lung cancer patients treated with surgery." (PMID 37120670, 2023). "Cytokines from BALF, particularly IL-6 and IL-12p70, show potential as diagnostic and prognostic biomarkers for lung cancer." (PMID 37373957, 2023). "Regression analysis demonstrated that IL-6 (cut-off = 25 pg/mL) and IL-12p70 (cut-off = 30 pg/mL) had the highest odds ratios for lung cancer risk, at 5.09 (95% CI: 2.38–9.24, p < 0.001) and 4.31 (95% CI: 1.85–8.16, p < 0.001), respectively." (PMID 37373957, 2023). "In mice lung cancer models, the presence of the Kras mutation led to the activation of the NF-κB pathway and to the secretion of IL-6 and IL-17, which was related to the increase in the IL-22 secretion." (PMID 37894302, 2023). "A study conducted in Australia and Sweden found that elevated IL-6 levels were linked to higher lung cancer risk in former and current smokers." (PMID 38067398, 2023). "The association between elevated levels of inflammatory markers (such as C-reactive protein, interleukin-1 and interleukin-6) and psychological distress have been well documented, and these markers are linked with an increased risk of lung cancer." (PMID 37519799, 2023). "Lung cancer was linked to elevated levels of the serum cytokines IL6 and IL8, and high levels of IL8 raised lung cancer risk." (PMID 36874133, 2023). "IL-6 (2nd generation) showed the highest odds ratio of 5.09 (95% CI: 2.38–9.24, p < 0.001), implying that patients with IL-6 levels above 25 pg/mL have a 5.09 times higher risk of lung cancer compared to those with lower levels." (PMID 37373957, 2023). "The risk of lung cancer increased for each unit increase in the natural log-transformed IL-6 (HR [95% CI]: 1.34 [1.17–1.54]), and IFN-γ (HR [95% CI]: 1.08 [1.01–1.16])." (PMID 38067398, 2023). "Lung cancer patients showed increased IL-6 and IL-8 levels in the serum, and the association was stronger among former and current smokers." (PMID 36140220, 2022). "In particular, IL-6 is involved in lung cancer tumorigenesis, and its increased circulating levels have been associated with poor survival of patients with lung cancer." (PMID 35742933, 2022). "Clinical investigations found increased serum levels of IL-6 were associated with lung cancer and lung cancer risk." (PMID 35448283, 2022). "Tobacco smoking is known to induce KRAS mutations and thereby stimulate IL-6 expression in the lung epithelium, promoting lung cancer cell proliferation and migration through the STAT3 pathway activation." (PMID 35742933, 2022). "AhR overexpression was associated with upregulation of IL-6 secretion, which is critical for lung cancer initiation." (PMID 35101137, 2022). "This is in line with the investigations of versican-induced lung-cancer metastasis, in which IL6 knockout caused only small differences in survival." (PMID 36224342, 2022). "Our main findings demonstrate and confirm the role of hepcidin and IL-6 in the pathogenesis of lung cancer-related anaemia, as well as present diagnostic values for hepcidin, IL-6, and CRP." (PMID 36612220, 2022). "For instance, elevated serum IL-6 and IL-8 levels were associated with shorter survival in patients with lung cancer." (PMID 36498497, 2022). "Consistent with our results in mouse models, high expression of ARG1 and IL6 associated with poor survival probability in lung cancer patients." (PMID 35778404, 2022). "Increased IL-6 levels are linked to frailty, and IL-6 increases the likelihood of lung cancer metastasis." (PMID 36276107, 2022).
lung carcinoma (continued). "Accumulation studies have shown that the levels of IL-1 β, IL-6, and IL-8 are all associated with the occurrence and development of lung cancer." (PMID 35928100, 2022). "In a preclinical study, lung cancer–induced osteoclastogenesis in vitro was associated with the upregulation of IL-6 and TNF-α and consequent activation of the AMPK/mTOR signaling pathway." (PMID 34950252, 2021). "Interleukin-6 (IL-6) is a proinflammatory cytokine that has been implicated in the progression of lung cancers, including KRAS-driven lung cancer." (PMID 34635780, 2021). "Lung cancer cells have been shown to be susceptible to polyI:C combined with inhibitors of IL6 and JAK2/STAT3." (PMID 33562773, 2021). "We further demonstrated that CAFs modulate lung cancer cell metastasis through IL-6/STAT3 and KRT8/AKT pathways, however, the underlying mechanism is not fully understood." (PMID 34552063, 2021). "Compared with IL-6, IL-1β is considered a promising biomarker that associates with clinical features of cachectic conditions in patients with gastrointestinal and lung cancer." (PMID 33925872, 2021). "The therapeutic inhibition of IL-6 in KRAS-mutated murine models of lung cancer reduced tumour progression and featured a decrease in tolerogenic macrophages, MDSCs and Tregs." (PMID 34944851, 2021). "In another study, higher baseline serum and bronchoalveolar lavage (BAL) fluid IL-8 and serum VEGF levels were associated with shorter survival, showing that lung cancer is associated with upregulation of IL-6 and IL-8." (PMID 34830880, 2021). "As a result, differences in the mutational status of lung cancer subtypes were expected to cause changes in the levels of cytokines IL-6 and TNF-α." (PMID 34439874, 2021). "Our previous studies also indicated that USP24 upregulation in lung cancer cells and the tumor-associated macrophages enhanced cancer malignancy through increases in IL6 expression and secretion via p300-mediated acetylation of histone H316." (PMID 33257797, 2020). "Serum CaN, OPG, PTHrP, IL-6, tP1NP, β-CTx, and tissue type were the univariate diagnostic factors for bone metastasis in lung cancer (P < 0.05); age and sex were the only two excluded factors." (PMID 32546271, 2020). "Another cytokine, IL-6, has been linked to Th17 cell differentiation and therefore would present an alternative pathway to modulate the tumor immune microenvironment in lung cancer patients." (PMID 33375062, 2020). "Here we investigated the involvement of DDIAS in IL-6–mediated signaling to understand the mechanism underlying the role of DDIAS in lung cancer malignancy." (PMID 31900385, 2020). "Elevated levels of IL-6, IL-8, and C-reactive protein are associated with the diagnosis of lung cancer." (PMID 33537234, 2020). "IL-6 deficiency diminished the migration and invasion-promoting effects of adipose stromal cells as well as lung cancer cells." (PMID 31491033, 2019). "In this study, we investigated the role of miR‐206 in IL6‐induced gefitinib‐resistant EGFR‐mutated lung cancer cell lines." (PMID 31507089, 2019). "The humanized IL-6Rab, tocilizumab, reduced plasma IL-6 levels, attenuated muscle loss, and restored levels of plasma albumin in lung cancer patients." (PMID 31010015, 2019). "This is consistent with previous reports that IL-6 and IL-11 expression and activated signaling pathways were positively linked with irradiation resistance in lung cancer, liver tumors, prostate cancer and leukemia." (PMID 31754344, 2019). "The mechanisms that underlie IL-6 increased metastasis and the effect of IL-6 treatment in lung cancer have been demonstrated in vitro and in vivo and similar results have been obtained for CXCL831,32." (PMID 31004093, 2019). "IL-6, a pro-inflammatory cytokine, is associated with suppression of prostate cancer metastases and is higher in patients with lung cancer." (PMID 28692671, 2017).
lung carcinoma (continued). "Consistent with an important role of IL-6 in inducing cachexia, there is an association between elevated tumor specific expression of IL-6 and poor prognosis of lung cancer patients where the prevalence of fatal cachexia is high." (PMID 28515477, 2017). "A higher lung cancer risk for participants with elevated concentrations of IL-6 was observed in recent clinical trial." (PMID 28676747, 2017). "We replicated the previous observations that IL-6 is associated with prognosis of lung cancer and extended its utility to prognosis in this highly-selected population of stage I lung adenocarcinoma patients." (PMID 28402963, 2017). "Elevated levels of IL-6 have been linked to decreased survival in breast, pancreatic, gastric, prostate, and lung cancers." (PMID 27901106, 2016). "IL-6 is of particular interest because it is expressed in malignant epithelial cells, and their expression is associated with a poor prognosis in lung cancer patients." (PMID 27375834, 2016). "The association between the IL6 promoter variants and increased risk for lung cancer was strongly supported by functional studies." (PMID 26372664, 2016). "Nevertheless, it has been reported that IL-10 and IL-6 polymorphisms increase the level of these proteins in serum, which correlates with higher number of cases of lung cancer." (PMID 27445423, 2016). "Despite that ataxia-telangiectasia mutated (ATM) is involved in IL-6 promoted lung cancer chemotherapeutic resistance and metastasis, the exact role of ATM in tumor necrosis factor-alpha (TNF-α) increasing tumor migration is still elusive." (PMID 27556690, 2016). "The aim of this study was to clarify the association between IL-6 rs1800796 polymorphism and risk of lung cancer." (PMID 24984610, 2014). "First, we measured serum IL-6 levels in patients with lung cancer and analyzed its association with cachexia and survival." (PMID 25010770, 2014). "In our study, there was significant between-study heterogeneity for association between IL-6 rs1800796 polymorphism and risk of lung cancer under all genetic models." (PMID 24984610, 2014). "Since there was significant between-study heterogeneity for association between IL-6 rs1800796 polymorphism and risk of lung cancer under all genetic models, we performed a meta-regression analysis to explore source of heterogeneity." (PMID 24984610, 2014). "We identified 21 potentially relevant articles concerning CRP or IL-6 in relation to lung cancer risk." (PMID 22912790, 2012). "Results from studies on IL-6 in relation to lung cancer risk were inconsistent, with both inverse and positive associations reported." (PMID 22912790, 2012). "Subsequently, several epidemiologic studies with large sample sizes or long-term follow-up have been performed regarding CRP, IL-6 and the risk of lung cancer." (PMID 22912790, 2012). "In a previous study, we have observed reduced expression of estrogen in lung cancer patients which was authenticated by the increased expression of IL-6 and high CYP1A1 polymorphism." (PMID 26316937, 2012). "During the last decade, several epidemiologic studies have evaluated the associations between CRP, IL-6 and lung cancer risk." (PMID 22912790, 2012). "This is supported by the evidence that increased circulating IL-6 levels are associated with lung cancer survival, and some reports that IL-6 is associated with tumor progression in several cancer types." (PMID 22912790, 2012). "Epidemiologic findings are inconsistent concerning the associations between C-reactive protein (CRP), interleukin 6 (IL-6) and lung cancer risk." (PMID 22912790, 2012). "We next examined IL-4, IL-5, IL-6, and IL-13 levels in BAL, since IL-4, IL-5, and IL-13 are major mediators of allergic inflammation and IL-6 gene polymorphisms have been associated with increased lung cancer risk in asthmatics." (PMID 20796309, 2010).
lung carcinoma (continued). "Lung cancer patients often exhibit elevated baseline inflammatory markers (e.g., IL-6, C-reactive protein) due to tumor-associated inflammation, which may amplify postoperative inflammatory responses and increase POAF risk." (PMID 40421295, 2025). "Elevated IL-6 levels have been connected with advanced disease stages, poorer prognosis, resistance to specific therapies, and cancer-associated cachexia in advanced lung cancer patients." (PMID 38276239, 2024). "Furthermore, high plasma IL-6 levels in lung cancer patients have been associated with immunotherapy resistance." (PMID 38983267, 2024). "In addition, IL-6 has been associated with lung cancer resistance to chemotherapy, and high serum IL-6 expression in lung cancer patients after chemotherapy is associated with a worse prognosis." (PMID 38424624, 2024). "Mechanistically, it was observed that a conditioned medium derived from cultured CAFs significantly enhanced the migration and invasion potential of lung cancer cells by secreting IL-6, regulating EMT-associated markers such as E-cadherin and vimentin expression." (PMID 36831295, 2023). "Notably, our study revealed that high IL-6 was associated with anti-PD-1/PD-L1 treatment-related adverse events in patients with lung cancer." (PMID 36831513, 2023). "Previous studies have found that the abnormal activation of STAT3 in the development of KRAS mutant lung cancer, which will be attenuated under anti-IL-6 therapy, suggesting a tight association between IL-6/STAT3 signaling and inflammation in KRAS-activated tumorigenesis." (PMID 36619616, 2022). "In a randomized controlled trial of an anti-IL-1β monoclonal antibody (CANTOS study), originally designed as a secondary prevention trial to reduce cardiovascular events, serum CRP and IL-6 were found to be associated with lung cancer incidence and with time to cancer diagnosis." (PMID 35406394, 2022). "In brief, IL-1 β, IL-6 and IL-8 are potential to be used as diagnostic biomarkers in lung cancer." (PMID 35928100, 2022). "Exhausted tumor-associated CD8+ T lymphocytes are another source of IL-6 in lung cancer." (PMID 35742933, 2022). "ApoC1 is a promising biomarker for diagnosing lung cancer and the underlying relationship between ApoC1 and IL-6, which may be explored to find novel therapies." (PMID 36506554, 2022). "In addition, lung cancer patients with an increase in plasma IL-6 level are found to be associated with immunotherapeutic resistance." (PMID 34093869, 2021). "Furthermore, Blt2 knockout (KO) in a mouse model of KRAS-driven lung cancer was associated with strong suppression of lung tumor formation and IL-6 production." (PMID 34635780, 2021). "The fact that curcumin administration in patients with cancer, including lung cancer, is strongly associated with a decreased level of inflammatory factors (interleukin 6 (IL-6), interleukin 8 (IL-8), and tumour necrosis factor alpha (TNF-α)) implies its strong potential for metastasis suppression." (PMID 34834295, 2021). "In addition, researchers utilising a KrasG12D-driven lung cancer murine model with genetic deficiency for IL-6 reported that the presence of oncogenic KRAS mutation leads to a reduction in tumour growth and improved survival." (PMID 33116132, 2020). "Changes in the IL-6 levels could be detected in lung cancer follow-up and were associated with patient overall survival." (PMID 33167343, 2020). "Indeed, FAS knockdown promoted nuclear translocation of p65 protein compared to those control cells, suggesting that NFkB activation by FAS knockdown is the main cause of increased IL6 expression in lung cancer cells." (PMID 32963220, 2020).